RHOA (ras homolog family member A)
Diseases named in the same sentence as RHOA in open-access papers (continued):
Sharing a sentence is not in itself a finding about the gene and the disease.
tumor (continued). "This study suggests that Fn infection stimulates tumor cells to produce exosomes enriched with miR-1246/92b-3p/27a-3p and CXCL16/RhoA/IL-8, which are then delivered to uninfected cells, promoting pro-metastatic behaviors." (PMID 39000577, 2024). "Through HIF‐1α/RhoA/ROCK1 signaling, DDR1 promoted cytoskeleton reorganization to induce tumor metastasis." (PMID 39024501, 2024). "METTL14 modifies TGFβ through the RhoA and PI3K-Akt pathways, which are considered to be related to tumor angiogenesis and tumor progression." (PMID 38053093, 2023). "Bioinformatics analysis and sequence alignments performed in our laboratory proposed that miR-3174 can target many influential tumor-promoting genes involved in the pathobiology of GBM, including CD44, PLAU, MDM2, CDK6 and RHOA." (PMID 37298284, 2023). "By reducing miR-122 and ZO-1 and enhancing RhoA and RhoA-GTP, F-actin expression and adhesion, and endothelial permeability, Circ-IARS overexpression boosted tumor invasion and metastasis." (PMID 37405480, 2023). "Inhibition of the RHOA/YAP pathway reduces the proliferation, invasion, and migration of malignant tumor cells in hepatocellular carcinoma." (PMID 37895915, 2023). "High expression of RAC1, RHOA, CDC42, and VEGFB were identified in metastatic subgroups, compared to primary tumor and normal lung epithelia clusters." (PMID 37202394, 2023). "In invading tumor cells, the small GTPase RhoA is activated in response to decreased ECM stiffness and promotes a shift towards a more amoeboid phenotype and the release of abundant tumor MVs from the membrane." (PMID 37760395, 2023). "The tools predicted several tumor-promoting genes as a potential target of miR-3174 including CD44, CDK6, MDM2, RHOA and PLAU." (PMID 37298284, 2023). "In addition to actin remodeling, the GEF-H1/RhoA/MLC2 pathway is also implicated in mediating inflammation, intercellular permeability, and cell adhesion, which are associated with reperfusion injury, epithelial or endothelial barrier failure, and tumor metastasis." (PMID 36834937, 2023). "Further, we also demonstrated that miR-3174 downregulates multiple tumor-promoting genes (CD44, MDM2, CDK6, RHOA and PLAU) and all of these have been reported to have an important role in the development of various malignancies, including GBM." (PMID 37298284, 2023). "In hepatocellular carcinoma cells, hypoxia promotes actin remodeling via the HIF-1α/RhoA/ROCK1 pathway and initiates EMT to facilitate tumor invasion and migration." (PMID 37864030, 2023). "miR-3174 downregulated the expression of multiple tumor-promoting genes including CD44, MDM2, RHOA, PLAU and CDK6." (PMID 37298284, 2023). "The RhoA/ROCK pathway is activated in a variety of tumors and exerts a direct regulatory effect on the mobility of tumor cells." (PMID 35101080, 2022). "CCR9/CCL25 can also activate Ras/Raf/MARK and RhoA/Rock signals to strengthen the degradation of ECM and change the cytoskeleton arrangement, thus enhancing tumor cell motility (Golec, Henao Caviedes & Baldwin, 2016)." (PMID 36003306, 2022). "After that, We investigated the difference in transcriptional expression of VAV1, RHOA, and ZC3HAV1 between tumor samples and adjacent normal liver tissues in various HCC datasets from TCGA, ICGC, and GEO14520." (PMID 36224658, 2022). "Nonetheless, the expression of VAV1, RHOA, and ZC3HAV1 in the tumor group was all up-regulated than that in the normal group in several HCC cohorts from Oncomine database." (PMID 36224658, 2022). "It was indicated that VAV1 expression was higher in normal tissues than in tumor samples, whereas, the elevated expression of RHOA and ZC3HAV1 was observed in the tumor group." (PMID 36224658, 2022). "These differential proteins were enriched in tumor-related pathways, including tumor growth, tumor invasion, immune response, metabolism, and signaling (RAC, FAK, CDC42, and RhoA) pathways." (PMID 35589723, 2022).
tumor (continued). "Furthermore, previous studies have also shown that RhoA silencing by small‐interfering RNA (siRNA) reduces proliferation and migration of tumour cells and may improve the cytotoxic effect of chemotherapy in human colon cancer cells, thereby reversing chemoresistance." (PMID 35277915, 2022). "Western blot analysis of the tumour samples from mice injected with siNC‐treated PanC‐1/NF co‐cultures revealed that exposure to 10 Gy irradiation resulted in a decrease in HNRNPC and RhoA protein expression, as well as increased p‐γH2AX levels." (PMID 35277915, 2022). "We have shown that tumor hypoxia stimulates the NPY/Y5R axis, which leads to RhoA over-activation, cytokinesis defects and polyploidy." (PMID 35484119, 2022). "They performed an acceptable analysis of the active state of RHOA-like and RAC1 in tumor samples, with the most complete examination of RHOC-GTP and RHOA-GTP levels in human breast tumor specimens." (PMID 35933373, 2022). "Rho family proteins including RhoA, CDC42, and Rac are key regulators of the actin cytoskeleton and play an important role in tumor metastasis." (PMID 36499486, 2022). "Four main signaling pathways are involved in SOX2 expression favoring tumor maintenance: TGF-β, SHH pathway, EGFRvIII, RhoA-dependent pathway and focal adhesion kinase (FAK) signaling." (PMID 36232992, 2022). "Specially, RhoA is involved in the cellular junction and TGF-β receptor signaling pathway according to the GO and KEGG analyses, which were driving factors in tumor progression." (PMID 35256884, 2022). "MH was able to restore the levels of RhoA and p-MLC in tumour cells in contact with the endothelium, suggesting a downregulation of adhesion and migratory and/or invasive properties." (PMID 36009536, 2022). "In mice with mutant Kras and deletion of Cdkn2a in lung epithelial cells, lung tumors develop with activation of ERK, RHOA, and FAK, and subsequent deletion or pharmacologic inhibition of FAK resulted in tumor regression." (PMID 35763345, 2022). "Increased stiffness promoted HSC activation by activating a RHOA-AKT-p300 mechanosignalling cascade and promoted transcription of more than 20 tumour-promoting factors." (PMID 34885024, 2021). "In humans, activation of RHOA in different cell types promotes CRC progression; this is the case of upregulated expression of GPR4 in the TME, or GEF-H1 in total tumor tissue." (PMID 33406731, 2021). "The mean percentage of positive tumor cells for c-MET, RhoA, and CLDN18 expression was 16.2% (SD ± 24, mean H-score = 20.7 ± 36.8), 36.2% (SD ± 30), and 35.0% (SD ± 29.9), respectively." (PMID 35076580, 2021). "Myosin contractility was necessary for US‐mediated tumor cell apoptosis and microtubule disruption enhanced myosin contractility through activation of GEF‐H1 and RhoA pathway." (PMID 34589605, 2021). "Many studies indicated that the expression of these proteins, including RHOA, RHOC, RAC1, RAC2 and CDC42 are upregulated and/or their activities are dysregulated through GEFs, GAPs or GDIs in tumor tissue." (PMID 33406731, 2021). "In this study, Rac1, RhoA and CDC42 were all required for tumour cell adhesion to the EC, but only CDC42 was required for the intercalation of tumour cells into the EC." (PMID 34374417, 2021). "In tumor cells of the WRC 256 strain, CTX inhibited RhoA and FAK kinase, thereby compromising the actin filament polymerization of these cells involved in the proliferation and adhesion of the tumor cell." (PMID 34421610, 2021).
tumor (continued). "Several studies have shown that RHOA and RHOC positively contribute to tumor promotion, but the distinct role of RHOB as a tumor suppressor or an oncogene in cancer remains elusive." (PMID 34771549, 2021). "RhoA was reported to impact activity of LIMK/cofilin cascade, an important signaling in tumor metastasis, by phosphorylation process." (PMID 33875796, 2021). "In a preliminary experiment we treated U87 tumour spheroids with either CCG-1423, or the RhoA inhibitor Rhosin HCl, or a combination of both inhibitors, which revealed a strong effect of both inhibitors in combination on cell invasion into collagen." (PMID 35052688, 2021). "Here we show that downregulation of RhoA expression rescued the RKIP-mediated inhibition of CCL5 expression and F4/80+ cells tumor infiltration." (PMID 34465801, 2021). "The expression of EpCAM in tumor cells could maximize the robustness of the RhoA cycle during its transit through the fast recycling endosomal pathway, thus ensuring that tensile forces are correctly generated at the cell scale and therefore supporting tumor propagation." (PMID 33850145, 2021). "We also found that the circARHGAP35 protein promoted tumor progression by interacting with TFII‐I, while ARHGAP35 inhibited cancer cell migration and invasion by limiting RhoA activity." (PMID 34258149, 2021). "We concluded that talaporfin sodium-based PDT induces the shutdown of existing tumor vessels via the RhoA/ROCK pathway by activating the Rho-GTP pathway and decreasing the tumor blood flow." (PMID 32825648, 2020). "The knockdown of DLC-1 increases GTP-bound RhoA and tumorigenic growth, and expression of constitutively active RhoA in these cells accelerate liver tumor formation, suggesting that DLC-1 acts as tumor suppressor." (PMID 32392742, 2020). "Therefore, by exerting an opposite effect on different pathways—inhibiting the TGF-β and RHOA/ROCK pathways, and activating PI3K/AKT/mTOR—miR-148a causes various functional consequences: It suppresses the development of metastases and increases the sensitivity of tumor cells to chemotherapy." (PMID 33142817, 2020). "Results also demonstrated that ζ-Stat decreased tumor growth by more than 50% by the endpoint of the experiment and decreased PKC-ζ and RhoA expression in tumors by more than 40%." (PMID 32175276, 2020). "p116RIP is a modulator of the RhoA/ROCK axis, a key pathway that promotes invasion and metastasis of tumor cells." (PMID 33240883, 2020). "Previous studies have shown that RhoA/Rac1 GTPase is an important link with Hippo, ERK, and PAK signaling pathways involved in tumor progression 27-34." (PMID 33042270, 2020). "Changes in protein content in transplanted tumor tissues were detected and it was found that E-cadherin, GEF-H1 and RhoA proteins changed with the variation in circ-133/GEF-H1/RhoA axis function." (PMID 32724467, 2020). "Studies on the role of actin and its interacting partners have highlighted key signaling pathways, RhoA/ROCK and its downstream effector proteins that, through the cytoskeleton, mediated tumor cell migration, invasion and metastasis." (PMID 33230171, 2020). "Increasing studies showed that both the Rho family and MMP family, including Rac1/2/3, CDC42, RhoA, RhoC, MMP2, and MMP9, are highly expressed in a variety of tumor tissues and are directly correlated with tumor migration and invasion." (PMID 33377649, 2020). "Its expression is increased in tumor tissues of patients and involved in the following pathways RET signaling and G-protein signaling_RhoA regulation." (PMID 32193399, 2020). "In tumor cells, EZH2 epigenetically represses negative regulators of mTOR (e.g., TSC2 and RHOA), thus inhibiting tumor cell autophagy and accelerating tumorigenesis." (PMID 32999031, 2020). "Conclusively, our results show that DEX treatment elevated ROR1 expression, which in turn enhanced RhoA, YAP/TAZ, and BMI-1 levels in OC tumor cells and is indicative of a DEX-mediated stemness phenotype via ROR1 signaling." (PMID 32989221, 2020).
tumor (continued). "Further studies showed that the role of ERM in tumor metastasis might result from a mTORC2-dependent pathway in which mTORC2 is found to modulate the actin cytoskeleton and promote migration and invasiveness through regulating RhoA activity, as is demonstrated previously." (PMID 33072782, 2020). "Subsequently, we examined the expression and the phosphorylation levels of ERK1/2, MEK1/2, PI3K, Akt, mTOR, FAK, RhoA, VEGFR2 and Tie2 in tumor tissue lysates." (PMID 31601793, 2019). "Starting from this observation, through bioinformatic analysis we focused our attention on miR-31-5p, which is reported to regulate the expression of HIF1AN, RhoA and RAC1 in different tumor cell lines and hMSCs." (PMID 30925808, 2019). "Moreover, the IHC test of RhoA showed that the hepatic cells in the normal tissue were mainly stained negatively except for portions of the interstitial substance (upper parts), while tumor cells in the HCC tissue from the same section were stained positively (lower parts)." (PMID 31339860, 2019). "Hypoxia can also contribute to the tumour progression in a HIF-independent manner via the activation of a complex signalling network pathway, including JAK-STAT, RhoA/ROCK, NF-κB and PI3/AKT." (PMID 31835751, 2019). "Consistent with the in vitro findings, EMT marker upregulation, RhoA downregulation, CD44 overexpression, and tumor phenotypes of ccRCC were observed in mice with chronic exposure to 3MC." (PMID 30872677, 2019). "NOV-002, the glutathione disulfide mimetic, was shown to suppress tumor cell invasion and metastasis via ErbB2, PI3K, Akt, and RhoA." (PMID 31683902, 2019). "A single dose of MSC-CM applied to SGC-7901 tumor cells resulted in tumor cell expression of VEGF and RhoA-GTPase and ERK1/2 activation leading to enhanced tumor growth that was maintained through serial transplantation experiments." (PMID 31075118, 2019). "We, for the first time, have demonstrated that SMG significantly inhibits cell focal adhesions and FAK/RhoA activity, and elucidated that SMG reduces tumor cell proliferation and metastasis via suppressing the FAK/RhoA-controlled mTORC1 pathway." (PMID 29986550, 2018). "Overexpression of circ-IARS significantly down-regulated miR-122 and ZO-1 levels, up-regulated RhoA and RhoA-GTP levels, increased F-actin expression and focal adhesion, enhanced endothelial monolayer permeability, and promoted tumor invasion and metastasis." (PMID 30064461, 2018). "To further investigate the roles of the circadian core protein CLOCK and BMAL1 in tumor cells, we performed immunofluorescence assays and found that both endogenous CLOCK (red) and BMAL1 (red) overlapped with RHOA (green), mainly in the cytoplasm." (PMID 30287810, 2018). "The effectors of RhoA, ROCK, and mDia1 promote this effect through enhanced actin polymerization, resulting in the dissociation of cell junctions to induce tumor invasion." (PMID 29659486, 2018). "Our data suggest ITGA9, as a suppressor of HCC, prevents tumor cell migration and invasiveness through FAK/Src-Rac1/RhoA signaling." (PMID 29951557, 2018).
tumor (continued). "Signaling by RhoA and its effector proteins Rho kinase-ROCKI and ROCKII promote amoeboid movement of tumor cells and the adoption of a more rounded shape." (PMID 30563499, 2018). "Tumor migration and invasion are strictly regulated by actin cytoskeleton modulated by Rho family of small GTPases, including RAC1, Cdc42, and RhoA in space timely." (PMID 29802377, 2018). "In this study, we demonstrate for the first time that CLOCK and BMAL1 promote cytoskeletal F-actin filament formation by regulating the RHOA-ROCK-CFL pathway, revealing a novel mechanism of circadian genes in tumor cells." (PMID 30287810, 2018). "The PCP pathway is relaying on RhoA and JNK activation, and more and more study have reported that Wnt signaling also participate in altering tumor cell metabolism to control cancer bioenergetics." (PMID 29108281, 2017). "The cooperation of RhoA/MMP-9 and Cdc-42/MT1 MMP pathways can form invadopodia of tumor cells activated by nuclear S100A4." (PMID 29069865, 2017). "The small Rho GTPases Rac1, RhoA and Cdc42, are key mediators in the Wnt/PCP pathway and important contributors to tumor migration and invasion." (PMID 26689985, 2016). "In the present study, we discovered the novel regulation pathway of miR-126, which for the first time validated the mechanism of miR-126 acts as tumor suppressor, via regulation of the CXCR4 and RhoA signaling pathway both in vitro and in vivo." (PMID 27517626, 2016). "However, the activation of RhoA may not necessarily be linked to the dissemination of tumor cells but rather may suppress migration." (PMID 27785353, 2016). "RHOA, SMAD2, SMAD4, SMAD5, SMAD6, BMPR1A, SMAD7 and MYC-, which thereby emerge as candidate genes to play an important role in CRC tumor metastasis." (PMID 27662660, 2016). "Cytokinesis failure leads to extra centrosomes that ultimately reduce RhoA activity in tetraploid cells, which in turn can activate the Large Tumor Suppressor Kinase 2 (LATS2) and the Hippo tumor suppressor pathway." (PMID 27731420, 2016). "Small GTPase RhoA and IGF1R have long been recognized to play an important role in tumorigenesis and tumor progression." (PMID 26151573, 2015). "This RhoA activation in lipin-1-depleted cells could be related to the increased concentration of PA which can activate the sphingosine kinase-1 to produce sphingosine-1-phosphate, a lipid mediator able to enhance RhoA activity, and to inhibit migration of various tumor cells including PC-3." (PMID 25834103, 2015). "Recent studies have shown that miR-124 mitigates tumor cell migration by directly targeting ROCK and Rac-1, both of which are components of the RhoA-ROCK cascade that regulates actomyosin contractility." (PMID 25969668, 2015). "The activity of ROCK is involved in the invasion and metastasis of tumor cells including colon cancer, in which ROCK is the main RhoA downstream effector." (PMID 26064956, 2015). "Downregulation of JWA was found to be crucial for the invasion and metastasis of human tumor through elevated FAK expression, the induction of RhoA and MMP-2 activation." (PMID 25925371, 2015). "In contrast, blocking RhoA activity significantly inhibits MMP2 and MMP9 expression, tumor invasion, and lung metastasis." (PMID 25889562, 2015). "We propose that the Rho-ROCK-MLCP pathway may be specifically upregulated in tumor cells as they encounter certain extracellular cues (such as compliant environments) that prompt the downregulation of Rac1 signaling along with a concomitant up-regulation of RhoA activation." (PMID 26458510, 2015).